NFE2L2 (NFE2 like bZIP transcription factor 2)
Diseases named in the same sentence as NFE2L2 in open-access papers (continued):
Sharing a sentence is not in itself a finding about the gene and the disease.
lung adenocarcinoma (28 papers, 2013 to 2025). A carcinoma that arises from the lung and is characterized by the presence of malignant glandular epithelial cells. "Genes in the KEAP1-NFE2L2 pathway are mutated in ~33% of lung squamous cell carcinoma and ~22% of lung adenocarcinoma, which agrees with our results indication the presence of NFE2L2 as activated upstream regulator both in ADC and SCC." (PMID 35512017, 2022). "In our study, multiplatform data from The Cancer Genome Atlas (TCGA) were acquired to identify two subtypes of lung adenocarcinoma harboring KEAP1/NFE2L2 mutations." (PMID 35371318, 2022). "In this study, the multiplatform data from TCGA were adopted to identify subsets of lung adenocarcinoma with KEAP1/NFE2L2 mutations." (PMID 35371318, 2022). "The KEAP1/NFE2L2 mutations, representing the dysfunctional activations of the stress response pathway, have been found in many malignant tumors, including lung adenocarcinoma 19-21." (PMID 35371318, 2022). "More research needs to be done to figure out the underlying molecular mechanism of mutations of the KEAP1/NFE2L2/CUL3 pathway in lung adenocarcinoma, and there is still a long way to go to target these mutations as a new therapeutic strategy." (PMID 34617407, 2021). "It is imperative to mine the underlying mechanisms and characteristics of KEAP1/NFE2L2/CUL3 mutations in lung adenocarcinoma and accelerate the investigations of the pathway and the targeted drugs." (PMID 34617407, 2021). "In the Keap1-mutated lung adenocarcinoma, activated Nrf2 (encoded by Nfe2l2) stabilizes Bach1 expression that further promotes invasion and metastasis of lung tumors." (PMID 33809182, 2021). "For example, combining clinical data and in vivo and in vitro approaches revealed the importance of KEAP1 and NFE2L2 mutations in lung adenocarcinoma, correlating them with advanced stages and worse survival." (PMID 33228209, 2020). "Similarly, two subtypes were identified in 20 lung adenocarcinoma cell lines harboring KEAP1/NFE2L2-mutations (C1 and C2 groups)." (PMID 35371318, 2022). "Therefore, our further research needs more samples to provide a more accurate subgroup analysis of KEAP1/NFE2L2/CUL3 pathway mutations so as to exhibit a deeper insight into KEAP1/NFE2L2/CUL3 pathway mutation in lung adenocarcinoma progression." (PMID 34617407, 2021). "KRAS-mutant lung adenocarcinomas often carried loss-of-function mutations in KEAP1, and co-mutations involving the PI3K-AKT-mTOR and NRF2 pathways, such as NFE2L2 amplification combined with loss of STK11, have also been observed." (PMID 40563292, 2025). "More than 400 drugs and compounds were tested on KEAP1/NFE2L2-mutant and wild-type lung adenocarcinoma cell lines in GDSC." (PMID 35371318, 2022). "Somatic mutations in the NFE2L2 (encoding NRF2) and KEAP1 genes have been described in 23% of patients with lung adenocarcinoma (LAC) and are usually mutually exclusive." (PMID 35814399, 2022). "Compared with the wild-type samples, lung adenocarcinoma harboring KEAP1/NFE2L2 had a significantly lower lymphocyte fractions (P = 0.001)." (PMID 35371318, 2022). "Two subtypes of KEAP1/NFE2L2-mutant lung adenocarcinoma were identified based on both patient and cell line samples, and genomic and clinicopathological features of KEAP1/NFE2L2 mutations were characterized." (PMID 35371318, 2022). "As previously stated in the Methods section, we integrated five data subtypes and clustered 89 KEAP1/NFE2L2-mutant lung adenocarcinoma patients into two subgroups (P1 and P2 groups)." (PMID 35371318, 2022). "For example, in lung adenocarcinoma (LAC) cohorts, patients who carried mutations in the KEAP1/NFE2L2 pathway had significantly shorter survival." (PMID 33109073, 2020). "Alterations in KEAP1/ NF-E2 p45-related factor 2 (NFE2L2/Nrf2) signaling pathway have been reported in 23% lung adenocarcinoma patients, suggesting that deregulation of the pathway is a major cancer driver." (PMID 31811110, 2019).
lung adenocarcinoma (continued). "Using a CRISPR/Cas-9-based approach in a mouse model of KRAS-driven lung adenocarcinoma, it was examined the effect of KEAP1 loss in lung adenocarcinoma development and hyperactivates NFE2L2 expression." (PMID 30060526, 2018). "Some genes significantly mutated were exclusively mutated in lung adenocarcinoma, such as STK11 (LKB1), RBM10, KEAP1, RIT1 and MET, while other genes such as NFE2L2, KDM6A, RASA1, NOTCH1 and HRAS are significantly mutated in LSQCC." (PMID 30060526, 2018). "Loss-of-function Kelch-like ECH-associated protein 1 (KEAP1) mutations or gain-of-function nuclear factor erythroid 2-related factor 2 (NFE2L2; also known as NRF2) mutations are found in ~20% of lung adenocarcinoma (LUAD) and in ~30% of lung squamous cell carcinoma (LUSC)." (PMID 38536921, 2024). "The biological features and intrinsic heterogeneities of KEAP1/NFE2L2-mutant lung adenocarcinoma remain unclear." (PMID 35371318, 2022). "The study explored intrinsic heterogeneities of KEAP1/NFE2L2-mutant lung adenocarcinoma." (PMID 35371318, 2022). "Moreover, the genomic alterations of KEAP1 and NFE2L2 were reported to play crucial roles in lung adenocarcinoma 13-15." (PMID 35371318, 2022). "Since KEAP1/NFE2L2/CUL3 gene mutations have not received enough attention in the clinical practice of lung adenocarcinoma, these three genes are not included in routine postoperative pathologic sample gene mutation detection in our hospital." (PMID 34617407, 2021). "Mutations in the KEAP1 or NFE2L2 genes are mutually exclusive and occur in NSCLC patients with a variable incidence (3.5–15% for KEAP1; 12–17% for NFE2L2), with the first ones mainly clustered with the lung adenocarcinoma (LUAD) histology." (PMID 32971994, 2020). "Type I and II LCNECs harbor key genomic alterations and oncogenic mutations, which are commonly found in SCLC, lung adenocarcinoma or squamous cell carcinoma (e.g., in RAS genes, BRAF, NFE2L2, as well as in STK11 and KEAP1 in the case of type I LCNECS, and RB1 losses in the case of type II LCNECs)." (PMID 29535388, 2018). "In addition, aberrations (mutations and amplifications) in the transcription factor NFE2L2 in six different tumour types (BLCA, head and neck squamous cell carcinoma, kidney renal clear cell carcinoma, lung adenocarcinoma, LUSC and UCEC) exhibited trans-effects on gene expression (P(D)≥0.8)." (PMID 26436532, 2015). "A recent study revealed that USP13 interacts with and catalyzes the deubiquitination of the transcription factor NFE2L2 and promotes an autophagy-to-ferroptosis switch in KRAS mutant lung adenocarcinoma." (PMID 41330897, 2025). "Genetic alterations to NFE2L2 and KEAP1 lead to constitutive activation of NRF2, that occurs in 30% of lung squamous cell carcinoma and 25% of lung adenocarcinoma." (PMID 37296863, 2023). "The initial results were validated by using in silico assessment of common lung adenocarcinoma cell lines, which revealed consistent features of KEAP1/NFE2L2-mutant subtypes." (PMID 35371318, 2022). "Generally, our study comprehensively analyzed the multiplatform data of TCGA to compare the biologic characteristics, intrinsic heterogeneities, and clinical features of the KEAP1/NFE2L2/CUL3 mutant and wild lung adenocarcinoma patients." (PMID 34617407, 2021). "Interestingly, LCNECs harbor also alterations of oncogenes which are commonly found in lung adenocarcinomas, but usually absent in neuroendocrine tumors like SCLCs, such as RAF family genes, BRAF and NFE2L2 mutations." (PMID 30060526, 2018).
Obesity (26 papers, 2013 to 2026). Accumulation of substantial excess body fat. "The NFE2L1 gene is also associated with obesity, and NFE2L2 overexpression results in weight loss and protection against diet‐induced obesity in transgenic mice." (PMID 38562019, 2024). "Collectively, these results demonstrate that miR-27a promotes hepatic steatosis by targeting NFE2L2, leading to mitochondrial impairment and oxidative stress, highlighting miR-27a as a potential biomarker and therapeutic target for obesity-associated liver metabolic disorders." (PMID 42197305, 2026). "Treatment with CDDO-Im prevented HFD-induced obesity, adipogenesis, and hepatic lipid accumulation in wild-type mice, but not in NFE2L2-deficient mice, indicating a potential therapeutic benefit of the NFE2L2-activating molecule." (PMID 35052597, 2021). "Mice deficient for Nfe2l2 have impaired adipogenesis and are protected from diet-induced obesity." (PMID 30777014, 2019). "The evidence for involvement of NFE2L2 in metabolic processes relevant to obesity and T2D is vast, with primary functions in protecting against oxidative stress and electrophilic stress, and regulating lipid metabolism and cell inflammatory responses." (PMID 41295283, 2025). "Nfe2l2-KO mice showed decreased adipose tissue with small adipocytes and are protected against weight gain and obesity induced by HFD." (PMID 35204118, 2022). "A transcription factor that has recently been implicated in obesity and metabolic dysregulation is Nrf2 (NFE2-related factor 2), encoded by NFE2L2 (nuclear erythroid factor 2-like 2)." (PMID 23710285, 2013). "Interestingly, we reported in male C57BL/6 J mice with obesity induced by high-fat/high-carbohydrate diet that prolonged-release pirfenidone decreased Nfe2l2 gene expression, and these mice showed improved systemic insulin sensitivity." (PMID 35204118, 2022). "Therefore, miR-34a-5p tightly modulated the development and progression of lipid accumulation in obesity-related diabetic steatohepatitis, and GA significantly inhibited hepatic lipogenesis by downregulating miR-34a-5p through targeting NFE2L2 in diabetic mice." (PMID 35052597, 2021). "Therefore, NAFL, but not obesity per se, was accompanied by the increased expression of NFE2L2 targets genes, including NOX4, which encodes a ROS-producing enzyme, and NQO1, SOD2, and CAT, which encode key antioxidant defense enzymes, but these declined with more advanced disease and fibrosis." (PMID 38060313, 2023). "Thus, mitochondria- and NOX4-derived ROS function in concert to drive a NFE2L2 antioxidant defense response to attenuate oxidative liver damage and progression to NASH and fibrosis in obesity." (PMID 38060313, 2023). "Thus, steatosis in obesity was accompanied by the induction of NOX4 and the NFE2L2 antioxidant defense response in hepatocytes." (PMID 38060313, 2023). "Another study investigated the effect on the NRF2 pathway of HFD-induced (39.7 kcal% fat) obesity among Nfe2l2-KO, WT, and Keap1-KD mice and concluded that the genetic alteration of Nfe2l2 does not prevent diet-induced obesity in mice." (PMID 35204118, 2022). "However, the deletion of Nfe2l2 in adipocytes led to a worsened systemic metabolic phenotype (increased glucose, cholesterol, and non-esterified fatty acids levels), whereas the deletion of Nfe2l2 in hepatocytes modestly reduced insulinemia after long-term HFD-induced obesity in mice." (PMID 35204118, 2022). "Moreover, except for NOX4 expression, which trended lower, NFE2L2, NQO1, SOD2, and CAT gene expression declined in patients with obesity (BMI = 47–74) with NASH and fibrosis (NAS = 5–6; fibrosis score = 1–2) to levels evident in patients with obesity with nonsteatotic livers." (PMID 38060313, 2023).
non-small cell lung carcinoma (24 papers, 2016 to 2026). A group of at least three distinct histological types of lung cancer, including non-small cell squamous cell carcinoma, adenocarcinoma, and large cell carcinoma. "The Kelch-like ECH-associated protein 1 (KEAP1) and the nuclear factor erythroid-2-related factor 2 (NFE2L2) mutations were found in more than 20% patients with non-small cell lung cancer, which represented one of the most important genomic subtypes 11,12." (PMID 35371318, 2022). "Furthermore, a pathogenic NFE2L2 mutation (p.D29V)-a genetic hallmark typically associated with oxidative stress response in non-small cell lung cancer (NSCLC) was identified." (PMID 42239895, 2026). "KEAP1/NFE2L2/CUL3 represented a mechanism of resistance to tyrosine kinase inhibitor in patients with EGFR-mutant non-small cell lung cancer." (PMID 35371318, 2022). "DUB USP11 reverses NFE2L2 polyubiquitination and stabilizes NFE2L2 to prevent oxidative stress-induced ferroptosis and promote tumorigenesis in non-small cell lung cancer cells." (PMID 36551253, 2022). "This review describes the mechanisms of targeted-drug resistance and newly identified non-small cell lung cancer targets (e.g., KRAS G12C, NGRs, DDRs, CLIP1-LTK, PELP1, STK11/LKB1, NFE2L2/KEAP1, RICTOR, PTEN, RASGRF1, LINE-1, and SphK1)." (PMID 36909198, 2023). "We used DeepCellEss to predict NFE2L2 under the options of ‘Non-Small Cell Lung Carcinoma’, ‘Squamous Cell Lung Carcinoma’, and ‘No-cancerous’ cancer types, respectively." (PMID 36458923, 2023).
Alzheimer disease (23 papers, 2016 to 2025). A progressive, neurodegenerative disease characterized by loss of function and death of nerve cells in several areas of the brain leading to loss of cognitive function such as memory and language. "NFE2L2 encodes NRF2 and NRF2 has proved to be activated in neurons and glial cells, but mainly in astrocytes, in patients with Alzheimer’s disease, Parkinson’s disease, amyotrophic lateral sclerosis, Huntington’s disease, and multiple sclerosis." (PMID 33419148, 2021). "Decreased Fpn expression and abnormal iron deposition significantly increased NOX4, 4-HNE, and MDA levels in damaged astrocytes of cerebral cortex, and five hub genes (JUN, SLC2A1, TFRC, ALB, and NFE2L2) closely related to ferroptosis were identified in Alzheimer's disease (AD) patients." (PMID 36062196, 2022).
atherosclerosis (22 papers, 2014 to 2026). A disease characterized by the build-up of fatty material and calcium deposition in the arterial wall resulting in partial or complete occlusion of the arterial lumen. "NFE2L2 is associated with atherosclerosis, AR is associated with coronary artery disease, and PTGS2 is associated with myocardial infarction." (PMID 36188612, 2022). "The cluster of miRNA BS in the NFE2L2 mRNA is one of the largest clusters of miRNAs associated with atherosclerosis-related genes in which BS are formed in the 5′ UTR." (PMID 33329752, 2020). "NFE2L2 is associated with pathophysiology of atherosclerosis and chronic obstructive pulmonary disease (COPD)." (PMID 24790085, 2014). "Several studies suggest that NFE2L2 alters susceptibility to atherosclerosis." (PMID 24790085, 2014). "Furthermore, the broad role of NFE2L2 in age-related diseases has been indicated by its association with the development of atherosclerosis and chronic obstructive pulmonary disease (COPD)." (PMID 24790085, 2014). "Then, KEGG pathway analysis revealed that these genes were enriched in “lipid and atherosclerosis” (Ncf1, Eif2s1, Tank, Vav1, Nfe2l2), “B-cell receptor signaling pathway” (Blnk, Dapp1, Vav1), and “Fc gamma R-mediated phagocytosis” (Prkcg, Ncf1, Vav1)." (PMID 38952478, 2024). "Freigang, S reported that NFE2L2 was essential for cholesterol crystal-induced inflammasome activation and exacerbation of atherosclerosis." (PMID 32320383, 2020). "NFE2L2 is an important component in antioxidant defenses in cardiovascular diseases such as atherosclerosis, hypertension, and heart failure." (PMID 30754631, 2019). "Although little information exists on this SNP and its association with COVID-19, several studies have demonstrated the involvement of NFE2L2 polymorphisms, which encode the NRF2 transcription factor, in cases of atherosclerosis, bronchial asthma, and chronic obstructive pulmonary disease." (PMID 36613859, 2022). "NFE2L2 may affect atherosclerosis development since it regulates hepatic lipid homeostasis via activation of lipogenic genes expression." (PMID 24790085, 2014). "Atherosclerosis is characterized by lipid deposition in the artery wall, and the impact of NFE2L2 on atherosclerosis development may be mediated by its role in lipid homeostasis." (PMID 24790085, 2014). "Considering oxidative stress contributes to the development of vascular diseases such as atherosclerosis, the lack of NFE2L2 regulon activation in coronary cells may provide insight into early disease onset and warrants further investigation." (PMID 40389438, 2025).
colon carcinoma (22 papers, 2012 to 2025). "It was found that DNASE1L3, ITGA5, BRAP, and NFE2L2 were related to the immune infiltration of colon cancer." (PMID 35252219, 2021). "Sulforaphane increased the expression of Loc344887 in HCT116 colon cancer cells by acting on the nuclear factor erythroid 2-related factor 2 (NFE2L2 or Nrf2)." (PMID 33805687, 2021). "In this study, we investigated the potential relationship between the cluster of differentiation (CD)-133, a CSC marker of colon cancer, and nuclear factor erythroid 2-like 2 (NFE2L2; NRF2), a master transcription factor for the regulation of multiple antioxidant genes." (PMID 35155201, 2021). "In 5-fluorouracil-resistant colon cancer models, upregulation of the histone methyltransferase MLL and its trimethylation product H3K4me3 correlates with enhanced NFE2L2 expression." (PMID 40868167, 2025). "On the other hand, it has been shown that NFE2L2 promoter demethylation resulted in NRF2 accumulation and chemoresistance in colon cancer cells." (PMID 33808001, 2021). "For this reason, we performed in vitro studies in colon cancer cells (SW-620) treated with RE to confirm and validate the specific effect of RE on decreasing the expression levels of JAK1, NFE2L2, CHKA, and BMP2 genes." (PMID 31450563, 2019).